RN7SL625P (RNA, 7SL, cytoplasmic 625, pseudogene)
Gene: Miscellaneous RNA gene on chromosome 7 (72,841,437 to 72,841,727, reverse strand). Ensembl gene ENSG00000274656.
Homologues: Orthologues: chimpanzee Metazoa_SRP (98% identical), guinea pig Metazoa_SRP (80% identical), macaque Metazoa_SRP (80% identical). Paralogues in human: RN7SL43P (96% identical), RN7SL2 (87% identical), RN7SL1 (86% identical), RN7SL3 (86% identical), RN7SL126P (84% identical), RN7SL769P (83% identical), RN7SL220P (82% identical), RN7SL448P (82% identical), RN7SL664P (82% identical), RN7SL798P (82% identical), RN7SL397P (82% identical), RN7SL652P (82% identical), and 702 more.